PRMT5 (protein arginine methyltransferase 5)
Diseases named in the same sentence as PRMT5 in open-access papers (continued):
Sharing a sentence is not in itself a finding about the gene and the disease.
neuroblastoma (14 papers, 2015 to 2025). Neuroblastoma (NB) is the most common solid, extracranial childhood tumor. "Our findings therefore identify PRMT5 as a potential therapeutic target for the treatment of high‐risk neuroblastoma." (PMID 39021294, 2025). "Our findings highlight that disruption of SNRPD3 protein methylation using PRMT5 inhibitors is a promising novel therapeutic target for the treatment of high-risk neuroblastoma, particularly given the observed SNRPD3- and MYCN-selectivity." (PMID 38049564, 2024). "MYCN-driven replicative stress has already been shown to increase susceptibility to PARP inhibition in neuroblastoma, further rationalizing the combination of PRMT5 and PARP inhibition for MNA neuroblastoma." (PMID 39313128, 2024). "PRMT5 inhibition significantly attenuates primary tumor growth and broadly blocks metastasis in multiple organs in xenograft tumor models of high-risk neuroblastoma." (PMID 35803962, 2022). "Further, PRMT5 is associated with MYCN (another member of the MYC family of transcription factors) in neuroblastoma cells and promotes its stability." (PMID 31694585, 2019). "Given the evidence for PRMT5 representing a collateral vulnerability for the MYC-family proteins from our lab and others we reasoned that pharmaceutical inhibition of PRMT5 may represent a promising targeted therapy for high-risk neuroblastoma." (PMID 39313128, 2024). "In this respect, it is noteworthy that in clinical neuroblastoma the expression of splicing and RNA processing factor genes was seen to coincide with PRMT5, E2F1 and MYCN levels, and similarly with some of the exon skipping events in the apoptotic genes." (PMID 39021294, 2025). "This question was of interest because previous studies have established that PRMT5 drives multiple oncogenic processes and is over‐expressed in diverse types of tumours including neuroblastoma." (PMID 39021294, 2025). "High expression of MYCN, PRMT5 and E2F1 in neuroblastoma cells derived from high‐risk disease causes a deregulated alternative RNA splicing programme and resistance to cell death." (PMID 39021294, 2025). "We show that MNA neuroblastoma is sensitized to PRMT5 inhibition in vitro and in vivo, adding to the recent evidence for the spliceosomal vulnerability of neuroblastoma." (PMID 39313128, 2024). "Together our study demonstrates the PRMT5-dependent spliceosomal vulnerability of MNA neuroblastoma and identifies the epitranscriptome and glutamine metabolism as critical determinants of this sensitivity." (PMID 39313128, 2024). "We sought to further develop our genetic interference data demonstrating PRMT5 requirement in MNA neuroblastoma by evaluating the highly selective, first-in-class PRMT5 inhibitor GSK3203591 on a panel of neuroblastoma cell lines." (PMID 39313128, 2024). "PRMT5 inhibition using GSK3326593 led to a significant improvement in survival in the Th-MYCN neuroblastoma mouse model and excellent target engagement was observed with strong SDMA reduction." (PMID 39313128, 2024). "Together our AS analysis strongly supports deregulation of splicing programmes by PRMT5 as an important factor in neuroblastoma growth and survival." (PMID 39313128, 2024). "We previously demonstrated that MYCN and PRMT5 proteins interact and PRMT5 knockdown led to apoptosis of MYCN-amplified (MNA) neuroblastoma." (PMID 39313128, 2024). "Together, our genetic interference and pharmacological inhibition data strongly suggest that PRMT5 is synthetically lethal with MYCN in neuroblastoma." (PMID 39313128, 2024). "We generated doxycycline-inducible shRNA to knock down PRMT5 expression in neuroblastoma cell lines." (PMID 35803962, 2022). "PRMT5 inhibition by GSK591 in the low nanomolar range significantly decreased the viability of three neuroblastoma cell lines representing the clinical diversity of neuroblastoma." (PMID 35803962, 2022).
neuroblastoma (continued). "We show that a PRMT5 inhibitor markedly reduces primary tumor growth and attenuates tumor cell metastasis to the liver, a common metastatic site for neuroblastomas." (PMID 35803962, 2022). "Our previous work demonstrated critical roles of PRMT1 and PRMT5 for neuroblastoma cell growth in part through arginine methylation of MYCN and subsequent enhancement of its stability." (PMID 32415090, 2020). "In human neuroblastoma cells, the metabolic enzyme protein arginine methyltransferase 5 (PRMT5) regulates cellular metabolism, protecting the cell in times of stress." (PMID 29312321, 2017). "The frequent over‐expression of PRMT5 in diverse human tumours, which includes neuroblastoma, and the critical role ascribed to E2F1 in the cancer cell cycle suggests that PRMT5 and E2F1 may play an important role in driving the malignant phenotype." (PMID 39021294, 2025). "Thus, high expression of the majority of genes from the DEG-DOWN signature associate with very poor prognosis in primary neuroblastoma, and PRMT5 inhibition lowers their levels in MNA neuroblastoma." (PMID 39313128, 2024). "Taken together, our metabolic studies strongly support the hypothesis that the PRMT5 dependency of MNA neuroblastoma is at least in part due to maintaining cancer cell fitness through glutamine addiction." (PMID 39313128, 2024). "The multiple levels of RNA regulation via these proteins, and of the hnRNPs, also known to interact with the epitranscriptomic machinery, suggests that the PRMT5-MYCN axis is also integral in proteostasis in neuroblastoma, which is supported by our global translation analyses." (PMID 39313128, 2024). "Taken together, these studies verify that expression of MYCN protein in neuroblastoma cells is a major determinant of GSK3203591 sensitivity, and further validate a MYCN-PRMT5 axis crucial to survival and proliferation of neuroblastoma as suggested previously using PRMT5 knockdowns." (PMID 39313128, 2024). "To investigate whether targeting SNRPD3 methylation is an effective therapeutic strategy in MYCN-amplified neuroblastoma we assessed the effects of the PRMT5 inhibitor, JNJ-64619178 in vitro." (PMID 38049564, 2024). "In the case of solid tumours, our group previously demonstrated that neuroblastoma cells over-expressing the MYCN oncogene are highly susceptible to loss of PRMT5, prompting this preclinical assessment of the selective PRMT5 inhibitors GSK3203591 and GSK3326593 in neuroblastoma." (PMID 39313128, 2024). "While testing the potential of AKT1-R391 being a substrate of PRMT5 in neuroblastoma, we found that the ectopic expression of AKT1-R391K mutant is significantly lower compared to AKT1 wild type and R15K mutant even in the presence of proteasome inhibitor MG132." (PMID 35803962, 2022). "Interestingly, previous reports suggested PRMT5 and N-Myc proteins physically interact and N-Myc protein stability is regulated by PRMT5 in neuroblastoma cells." (PMID 32292506, 2020). "Small‐molecule inhibitors of PRMT5 may therefore represent a novel therapeutic strategy for neuroblastoma and other cancers driven by the MYCN oncogene." (PMID 25475372, 2015). "Since E2F1 is a biological target for PRMT5, and because PRMT5 is over‐expressed in neuroblastoma, we reasoned that an important relationship may exist between the two genes that contributes to the aetiology of neuroblastoma." (PMID 39021294, 2025). "Consequently SNRPD3, MYCN, and PRMT5 expression levels may be used as predictive biomarkers for PRMT5 inhibitor response, not only in neuroblastoma, but potentially other cancers." (PMID 38049564, 2024). "In addition, PRMT5 knockdown significantly impaired neuroblastoma cell viability." (PMID 35803962, 2022). "The pharmacological inhibition of PRMT5, or E2F1 inactivation, restores normal splicing, rendering neuroblastoma cells sensitive to apoptosis." (PMID 39021294, 2025).
neuroblastoma (continued). "The PRMT5 inhibitor GSK3203591 inhibits growth and induces apoptosis in neuroblastoma, accompanied by changes in the DNA damage response, epitranscriptome and metabolism, and reduces GLS expression." (PMID 41244073, 2025). "In summary, our in vivo data demonstrate that GSK3326593 is a highly selective Prmt5 inhibitor, and that inhibition of Prmt5 in MYCN-dependent mouse neuroblastoma compromises the fitness and proliferation of tumour cells, resulting in their increased survival." (PMID 39313128, 2024). "Previous work in our laboratory demonstrated that MNA neuroblastoma cell survival was dependent on protein arginine methyltransferase 5 (PRMT5), with knockdown of PRMT5 resulting in MNA neuroblastoma cell line apoptosis." (PMID 39313128, 2024). "Here we evaluate the highly selective first-in-class PRMT5 inhibitor GSK3203591 and its in vivo analogue GSK3326593 as targeted therapeutics for MNA neuroblastoma." (PMID 39313128, 2024). "PRMT5 has recently been shown to control intron retention of METTL3 in blastic plasmacytoid dendritic cell neoplasm, similar to our observations in neuroblastoma." (PMID 39313128, 2024). "As our previous immunohistochemical analyses of primary tumours had demonstrated very high nuclear PRMT5 in poor prognosis MNA neuroblastoma, in contrast to predominantly cytoplasmic PRMT5 in other neuroblastomas, we focused on nuclear deregulatory events." (PMID 39313128, 2024). "Based on our findings we propose that targeting PRMT5 will limit AKT1 activation, metastases, and drug resistance of neuroblastoma and other aggressive cancers." (PMID 35803962, 2022). "MYCN-amplified tumors exhibited high levels of PRMT1 and PRMT5; knockdown of either PRMT1 or PRMT5 led to downregulation of MYCN and suppression of cell growth, suggesting a dependence of MYCN-amplified neuroblastoma on PRMTs3,4." (PMID 32415090, 2020). "PRMT5 has also been shown to methylate N-MYC and alter its protein stability as well as enhance its oncogenic activity in neuroblastoma." (PMID 30613353, 2018). "We investigated the relevance of PRMT5 and E2F1 in neuroblastoma (NB) and found that elevated expression of PRMT5 and E2F1 occurs in poor prognosis high‐risk disease and correlates with an amplified Myelocytomatosis viral‐related oncogene, neuroblastoma‐derived (MYCN) gene." (PMID 39021294, 2025). "Indeed, the current study showed that the PRMT5 inhibitor, JNJ-64619178, is effective against neuroblastoma cell lines and demonstrated SNRPD3- and MYCN-dependency." (PMID 38049564, 2024). "Together these findings suggest that MYCN, SNRPD3, and PRMT5 proteins may cooperatively complex to enhance SNRPD3 methylation and spliceosome assembly in MYCN-driven neuroblastoma." (PMID 38049564, 2024). "These signatures suggest that PRMT5-mediated epigenetic silencing is unlikely to be the major determinant of MNA neuroblastoma sensitivity to GSK3203591." (PMID 39313128, 2024). "We hypothesise that a similar mechanism is utilised in neuroblastoma to maintain splicing fidelity, where MYCN increases the expression of PRMT5, SNRPD3, and SNRPD3 methylation." (PMID 38049564, 2024). "Indeed, the PRMT5 inhibitor, JNJ-64619178, reduced cell viability and SNRPD3 methylation in neuroblastoma cells with high SNRPD3 and MYCN expression." (PMID 38049564, 2024). "As we mostly observed inhibition of cell growth rather than pronounced apoptosis, suggesting that PRMT5 may support the metabolic fitness of MNA neuroblastoma, we were intrigued by the consistent PKM2-PKM1 splicing switch observed after PRMT5 inhibition." (PMID 39313128, 2024). "Our work demonstrates that PRMT5 activity is integral to regulation of transcriptional and alternative splicing programmes in MNA neuroblastoma, functioning to regulate key survival and fitness programmes, including cellular metabolism, DNA repair and epitranscriptome modulation." (PMID 39313128, 2024).
neuroblastoma (continued). "As PRMT5 inhibitors affect other protein methylation events, we assessed whether JNJ-64619178 effects on neuroblastoma cell viability were dependent on SNRPD3 in neuroblastoma cells." (PMID 38049564, 2024). "Taken together, these data indicate a significant inhibition of neuroblastoma metastatic spread upon PRMT5 knockdown that is independent of primary tumor growth." (PMID 35803962, 2022). "In good agreement with previous studies, we observed in multiple and diverse PRMT1-depleted human neuroblastoma cell lines an increase of sDMA levels along with the expected decrease of aDMA levels, with no detectable change of PRMT5 protein level." (PMID 32415090, 2020). "Here, we wanted to elucidate the role that PRMT5, E2F1 and MYCN may take on in neuroblastoma." (PMID 39021294, 2025). "To address whether there was any potential clinical significance in the levels of PRMT5 and E2F1, we examined gene expression in a collection of 649 human neuroblastoma biopsies taken from early and late (stage 1 to 4) disease and calculated survival probability curves." (PMID 39021294, 2025). "As PRMT5 inhibition was demonstrated to have marked effects on epitranscriptomic regulators, we next explored whether global translation was affected by GSK3203591 in MNA neuroblastoma cells." (PMID 39313128, 2024). "In addition, PRMT5 methylates AKT1 on Arg 15 in the PH domain, promoting AKT1 translocation to the plasma membrane and subsequent phosphorylation at Thr308 and Ser473 in neuroblastoma." (PMID 36499164, 2022). "The dual inhibition of PRMT1 and PRMT5 has not yet been evaluated in neuroblastoma." (PMID 32415090, 2020). "PRMT5 is known to exert epigenetic silencing through histone 3 arginine methylation, but our DEGs suggest that epigenetic derepression via PRMT5 inhibition is not a major route of drug action in MNA neuroblastoma." (PMID 39313128, 2024). "Indeed, we found that the currently available PRMT5 inhibitors, such as EPZ015666 were not able to recapitulate the sensitivity of human neuroblastoma cells in response to depletion of PRMT1 or PRMT5 (data not shown)." (PMID 32415090, 2020).
triple-negative breast carcinoma (13 papers, 2017 to 2025). An invasive breast carcinoma which is negative for expression of estrogen receptor (ER), progesterone receptor (PR), and human epidermal growth factor receptor 2 (HER2). "Triple-negative breast cancer (TNBC) exhibits heterogeneous responses to PRMT5 inhibition, posing challenges for therapeutic targeting." (PMID 41255229, 2025). "KEAP1 is specifically methylated by protein arginine methyltransferase 5 (PRMT5) in triple-negative breast cancer cells, inhibiting intracellular iron transport." (PMID 38853203, 2024). "In triple-negative breast cancer, PRMT5 functions as a master transcriptional coregulator of the glucocorticoid receptor regulating cell migration after dexamethasone treatment." (PMID 37536978, 2023). "Here we report that autophagy blockage enhances cellular sensitivity to PRMT5 inhibitor in triple negative breast cancer cells." (PMID 37400460, 2023). "For instance, in triple-negative breast cancer, the small molecule inhibitor WX2-43 blocks KLF4 methylation by inhibiting the Protein Arginine Methyltransferase 5 (PRMT5) -KLF4 interaction, showing significant antitumor efficacy." (PMID 39995670, 2025). "In addition, PRMT5 is heterogeneously expressed in triple-negative breast cancer (TNBC); and inhibition of PRMT5 triggers apoptosis and regulates cell cycle progression." (PMID 34124017, 2021). "Moreover, this lack of effect of PRMT5 deletion or inhibition on MCF10A self-renewal was not due to receptor status, as treatment of the triple-negative breast cancer cells SUM159 with GSK591 phenocopies that of MCF7 cells, reducing both BCSC proliferation and self-renewal." (PMID 29262329, 2017).
bladder cancer (12 papers, 2018 to 2026). "Recently, WDR5 was also reported to be involved in lymphatic metastasis in bladder cancer through heat shock factor 1 (HSF1)–protein arginine methyltransferase 5 (PRMT5)–WDR5 axis." (PMID 37568727, 2023). "CircRNAs such as circ-PRMT5 (hsa_circ_0031242) produced by the PRMT5 gene promote bladder cancer development by regulating EMT through sponging up miR-30c." (PMID 36144454, 2022). "The relationship between PRMT5 expression and clinicopathological characteristics in bladder cancer." (PMID 32392182, 2020). "Circular RNA PRMT5 sponges miR-30c and promotes bladder cancer progression by inducing epithelial-mesenchymal transition (EMT)." (PMID 32457613, 2020). "Circular RNA PRMT5 promotes the metastasis of bladder cancer by inducing EMT and can also be secreted into exosomes and detected in urine." (PMID 32457613, 2020). "For example, the circular RNA PRMT5 promotes the metastasis of bladder carcinoma by sponging miR-30c and induces epithelial-mesenchymal transition." (PMID 31719211, 2019). "We found here that PRMT5 can reduce bladder cancer cell apoptosis by upregulating NF-κB activity, thereby potentiating cellular proliferation." (PMID 30713476, 2018). "We described here that PRMT5 is highly expressed in bladder cancer cell lines and primary human bladder cancer tissues." (PMID 30713476, 2018). "Our work thus demonstrated PRMT5 is crucial for facilitating bladder cancer growth, and is an important target for cancer therapy." (PMID 30713476, 2018). "Our findings that PRMT5 inhibition induced cell apoptosis and growth suppression further confirmed that PRMT5 contributes directly to manifestation of the malignancy in human bladder cancer." (PMID 30713476, 2018). "Our results demonstrate the carcinogenic function of the PRMT5/NF-κB signaling in bladder cancer and the role of PRMT5 inhibitor as a potent agent for the strategic therapy for bladder cancer." (PMID 30713476, 2018). "Chromatin immunoprecipitation (ChIP) was performed using T24 bladder cancer cells treated with EPZ015666 to address critical roles of PRMT5 on NF-кB recruitment." (PMID 30713476, 2018). "Overall, these results support a model in which NF-kB-dependent anti-apoptotic genes c-IAP1 and BCLXL are crucial for PRMT5-mediated tumor growth in human bladder cancer." (PMID 30713476, 2018). "Collectively, the current suggests the crucial role of PRMT5 as a promising therapeutic target in bladder cancers." (PMID 30713476, 2018). "To examine if PRMT5 is a tumor promoter in bladder cancer, we first tested PRMT5 protein expression in bladder cancer cell lines." (PMID 30713476, 2018). "We next detected if apoptosis contributes to decreased cell proliferation in PRMT5 knockdown bladder cancer cells." (PMID 30713476, 2018). "In conclusion, our work illustrated that PRMT5 is highly expressed in bladder cancer cell lines and patients." (PMID 30713476, 2018). "Compared to human normal bladder cell lines HBSMC and SV-HUC-1, PRMT5 protein levels were much higher in human bladder cancer cells (T24 and UM-UC-3)." (PMID 30713476, 2018). "Notably, flavokawain A, a natural product, has been reported to be a potential PRMT5 inhibitor and is applicable for the treatment of bladder cancer." (PMID 41362736, 2026). "Importantly, PRMT5 inhibition significantly represses bladder cancer cell proliferation and invasive bladder cancer growth by activation of critical NF-кB dependent anti-apoptotic genes." (PMID 30713476, 2018). "PRMT5 enhances the proliferation and colony formation of bladder cancer cells." (PMID 30713476, 2018). "The primary human bladder cancer tissues were further used to detect PRMT5 protein levels." (PMID 30713476, 2018). "Notably, in the current study, overexpression of PRMT5 was observed in both human bladder cancer cell lines and patients." (PMID 30713476, 2018). "We therefore propose that PRMT5 is a promising drug target in bladder cancer." (PMID 30713476, 2018).